IRAK4 (interleukin 1 receptor associated kinase 4)
Diseases named in the same sentence as IRAK4 in open-access papers (continued):
Sharing a sentence is not in itself a finding about the gene and the disease.
gram-positive bacterial infections (1 paper, 2013). Infections caused by bacteria that retain the crystal violet stain (positive) when treated by the gram-staining method. "While the minor variant of this SNP has been associated with Gram-positive bacterial infections, this report is the first to correlate this or any IRAK4 polymorphism with BrCa risk." (PMID 24194738, 2013).
Headache (1 paper, 2023). Cephalgia, or pain sensed in various parts of the head, not confined to the area of distribution of any nerve. "However, headaches are not a clinical manifestation in IRAK4 null individuals, and the highly selective nature of IRAK4 degradation with KT-474 makes off-target effects as the cause of headaches unlikely." (PMID 37957373, 2023).
hemophagocytic lymphohistiocytosis (1 paper, 2025). "Diagnoses of early deceased patients with PIRD (n = 70 under 5 years of age) were mostly due to disorders with a high risk of hemophagocytic lymphohistiocytosis (81.4%); premature deaths in “innate” IEI were frequently due to IRAK4 or MyD88 deficiencies." (PMID 41347188, 2025).
hyper-IgE syndrome (1 paper, 2025). A condition that is characterized by elevated serum IgE, dermatitis, and respiratory infections. "Certain conditions, such as defects in the IL-1R/TLR pathway (e.g., IRAK-4 deficiency), leukocyte adhesion deficiency, or hyper-IgE syndrome (STAT3 deficiency), can predispose individuals to severe and invasive Staphylococcal infections." (PMID 41431004, 2025).
IgG4-related disease (1 paper, 2025). "In IgG4-related disease (IgG4-RD), CD163+ M2 Mφs promote fibroblast activation and fibrosis by releasing profibrotic cytokines (e.g., IL-33, TGF-β) through the TLR7/IRAK4/NF-κB pathway." (PMID 41164198, 2025). "In IgG4-related disease, TLR7+ CD163+ M2 Mφs directly drive fibrosis by secreting TGF-β and other profibrotic factors via the TLR7/IRAK4/NF-κB pathway." (PMID 41164198, 2025).
Insulin resistance (1 paper, 2018). Increased resistance towards insulin, that is, diminished effectiveness of insulin in reducing blood glucose levels. "Exposure of high-fat-fed mice to TMA reduced low-grade inflammation and insulin resistance via inhibition of interleukin-1 receptor-associated kinase 4 (IRAK-4)." (PMID 29678198, 2018).
juvenile idiopathic arthritis (1 paper, 2021). Juvenile idiopathic arthritis (JIA) is the term used to describe a group of inflammatory articular disorders of unknown cause that begin before the age of 16 and last over 6 weeks. "However, Hugle reported a case of a patient with antinuclear antibody (ANA)-positive juvenile idiopathic arthritis with genetically confirmed IRAK4 deficiency." (PMID 33083971, 2021).
leukocytosis (1 paper, 2014). "In many IRAK-4-deficient patients clinical and laboratory signs of inflammation (such as CRP, IL-6, leukocytosis) develop slowly even in instances of severe infection, as seen in the first sibling in our study." (PMID 24625087, 2014).
nasal polyps (1 paper, 2012). "As for the subgroup analysis for the presence of nasal polyps (CRSwNP and CRSsNP) displayed significant association in CRSwNP cohorts regarding to one SNP in RYBP (rs4532099) and 5 SNPs IRAK4 (rs4252431, 6582484, rs1461567, rs4251559 and rs3794262)." (PMID 22723975, 2012).
Obesity (1 paper, 2025). Accumulation of substantial excess body fat. "Here, we show that the microbial metabolite trimethylamine (TMA) decouples inflammation and IR from diet-induced obesity by inhibiting interleukin-1 receptor-associated kinase 4 (IRAK4), a central kinase in the Toll-like receptor pathway sensing danger signals." (PMID 41361024, 2025). "Our work can guide human trials in which the efficacy of IRAK4 inhibitors available for human use or dietary interventions that increase TMA bioavailability can be evaluated in the context of obesity and IR." (PMID 41361024, 2025).
oral diseases (1 paper, 2024). "However, further studies are needed to investigate whether targeting IRAK-4 provides an effective approach for treating immune-inflammatory responses and bone resorption in oral diseases in vivo." (PMID 39126003, 2024).
peritonitis (1 paper, 2024). Inflammation of the peritoneum (tissue that lines the abdominal wall and covers most of the organs in the abdomen). "In conclusion, DW18134 could potentially treat acute peritonitis by reducing macrophage infiltration, regulating the NF-κB signaling pathway through targeting IRAK4, and subsequently inhibiting the expression of inflammatory cytokines to ameliorate pathological injury." (PMID 38675622, 2024). "In this study, we developed a novel IRAK4 inhibitor, DW18134, which exhibited considerable anti-inflammatory activity in vitro and alleviated symptoms of acute peritonitis and IBD in vivo." (PMID 38675622, 2024). "In conclusion, our findings reported a novel IRAK4 inhibitor, DW18134, as a promising candidate for treating inflammatory diseases, including peritonitis and IBD." (PMID 38675622, 2024).
renal carcinoma (1 paper, 2013). A carcinoma arising from the epithelium of the renal parenchyma or the renal pelvis. "IRAK4 was first observed in the serum of both normal individuals and those with renal carcinoma." (PMID 24194738, 2013).
Respiratory tract infection (1 paper, 2021). An infection of the upper or lower respiratory tract. "Probiotic treatment significantly upregulates the expressions of TLR7, MyD88, IRAK4, TRAF6, and NF-κB to alleviate FM1 influenza virus-induced respiratory tract infection." (PMID 33924002, 2021).
Salmonella Infections (1 paper, 2025). Infections with bacteria of the genus SALMONELLA. "The “Salmonella Infection” pathway includes HSP90AB1, IRAK4, and PIK3C2A, focusing on host-pathogen interactions and inflammation." (PMID 40621499, 2025).
sarcoma (1 paper, 2025). A usually aggressive malignant neoplasm of the soft tissue or bone. "In the sarcoma group, variants of IRAK4 were identified, which activated the NF-κB signaling pathway." (PMID 40446009, 2025).
skin inflammation (1 paper, 2024). "Overall our results demonstrate that blockage of the IRAK4 signaling can suppress the DNFB-induced AD-like skin inflammation both in TDDs and p.o., implying their potential and clinical significance." (PMID 38904012, 2024). "While the DNFB-induced AD-like skin inflammation was attuned after treated with the inhibitor of IRAK4." (PMID 38904012, 2024). "Our study demonstrate that IL-38 depends on IL-36R activates the IRAK4/NF-κB signaling pathway, which in turn up-regulates CCR7, facilitating the migration of LCs, in thus promotes the development of DNFB-induced AD-like skin inflammation." (PMID 38904012, 2024).
Stroke (1 paper, 2021). Sudden impairment of blood flow to a part of the brain due to occlusion or rupture of an artery to the brain. "Since microglial activation is ubiquitous in various neuroinflammatory diseases including stroke, targeting IRAK4 phosphorylation has potential translational value." (PMID 33573200, 2021).
T-cell acute lymphoblastic leukemia (1 paper, 2022). Acute lymphoblastic leukemia of T-cell origin. "Activation of inflammatory response pathways via IRAK1 and IRAK4 are also reported in MDS, AML, T cell acute lymphoblastic leukemia, and lymphoma." (PMID 35022428, 2022).
Thrombocytopenia (1 paper, 2021). A reduction in the number of circulating thrombocytes. "Compared with that in the control group, the expression of TLR7, MyD88, IRAK4, and TRAF6 increased significantly in the B cells of patients with pSS associated thrombocytopenia (p < 0.05)." (PMID 33767707, 2021).
infection (38 papers, 2008 to 2025). The state of being infected such as from the introduction of a foreign agent such as serum, vaccine, antigenic substance or organism. "Individuals with IRAK4 mutations, for example, show an increased sensitivity to infections, specifically in the upper respiratory tract." (PMID 37997696, 2023). "Globally, MyD88/IRAK-4–deficient patients were less likely to develop severe infections (mild infections: 27.3 vs. 5.7%; moderate: 27.3 vs. 2.9%; severe: 18.2 vs. 11.4%; critical: 27.3 vs. 80%; P = 0.0002)." (PMID 36880831, 2023). "IRAK4 deficiency is an inborn error of immunity predisposing patients to invasive pyogenic infections." (PMID 33083971, 2021). "More proximal loss-of-function defects, such as those found in TLR3 or in the adaptors MyD88 and IRAK-4, are associated with a restricted cadre of infections." (PMID 34199501, 2021). "Importance of IRAK-4 is suggested by the description of an enhanced susceptibility to infection with gram-positive bacteria in IRAK-4 deficient children." (PMID 22723975, 2012). "IRAK4 knockout mice are also more susceptible to infections by (Gram positive) S. aureus than wild-type mice." (PMID 20105294, 2010). "It should however be noted that infections in patients with IRAK4-deficiency are pyogenic (pus-forming) and can lead to mild fever and inflammation at late stages of infection." (PMID 20105294, 2010). "These mice, like IRAK4-deficient children, are susceptible to infections by Gram positive bacteria and fail to produce inflammatory cytokines in response to LPS." (PMID 20105294, 2010). "This in vivo evidence implies that certain inflammatory mediators must have been produced and that cells are actively recruited to the site of infection in IRAK4-deficient individuals." (PMID 20105294, 2010). "Recent data from patients with inherited MyD88 and IRAK-4 deficiencies during the COVID-19 pandemic highlight their vulnerability to severe hypoxemic viral pneumonia and emphasize the need for aggressive supportive care and infection prophylaxis." (PMID 41369391, 2025). "Thus, transcriptomic analysis demonstrated that the MyD88/IRAK-4–deficient patients were able to mount a systemic inflammatory response during the acute phase of the infection." (PMID 36880831, 2023). "Delayed diagnosis and inappropriate treatment of patients with IRAK4 deficiency may not only lead to fatal invasive infection but also to irreversible organ damage later in life." (PMID 33083971, 2021). "Lower IRAK4 gene expression in the NE infants implies that NE infants may have an increased susceptibility to infection, demonstrating that NE infants have an adaptable response to limit hyperinflammation." (PMID 33659224, 2020). "In most patients with IRAK4 deficiency, the first infection presents before 2 years of age." (PMID 33659224, 2020). "Our results suggest that NE infants are more likely to have IRAK4 deficiency than controls and may have increased susceptibility to infection." (PMID 33659224, 2020). "Moreover, mice deficient of or with modified versions of TLR2, TIRAP, MyD88 and/or IRAK4 were more susceptible to infection with Staph. aureus, En. faecium and/or Strep. pneumoniae infection." (PMID 23873783, 2013). "However, patients with MyD88- or IRAK4-deficiencies are highly susceptible to infections by Gram-positive bacteria, while they have normal resistance to Gram-negative bacteria and other pathogens." (PMID 23873783, 2013). "Furthermore, while MyD88- and IRAK-4-deficient children are at risk of life-threatening invasive bacterial infections early in life, with a mortality rate of approximately 38%, the susceptibility to infection decreases significantly with age." (PMID 34199501, 2021). "Therefore, patients treated with an IRAK1-specific inhibitor might have a reduced risk for infection by microbial pathogens than patients treated with an IRAK4 inhibitor." (PMID 27807192, 2016).
infection (continued). "As demonstrated here, the expression of IL-8/CXCL8, Gro-α/CXCL1, MCP-2/CCL8 and MIP-3α/CCL20 was compromised in LPS-stimulated IRAK4-deficient monocytes, suggesting a diminished recruitment of neutrophils, monocytes, lymphocytes, basophils and eosinophils to sites of infection." (PMID 20105294, 2010). "For the TLR pathway, one TLR homolog, the adaptor molecule MyD88, TRAF6, kinase IRAK4 and two transcription factors IкB-α and NF-кB were all significantly upregulated after 6 h and 12 h of infection." (PMID 32276269, 2020). "The accumulation of IRAK-4 proteins in the area of infection and the activation of IRAK-4 kinase activity follow this process." (PMID 30997787, 2019). "Our findings indicate that these therapies have to focus on reducing the IRAK4 expression, or protein quantity, during the infection to lower the inflammatory response." (PMID 27432718, 2016). "Of note, infectionsdecrease in IRAK-4-deficient children >8 years of age, suggesting a greaterdependency early in life on TLR signaling for protection against infection." (PMID 21533209, 2011). "Theoretically, TLR agonists could compensate for the absence of key proteins in signaling pathways, such as MyD88 or IRAK-4, restoring a patient’s ability to fight infections." (PMID 41369391, 2025). "A link between TLR signalling and epithelial barrier function via IRAK4 signalling has been well described during infection progression, although stimulation of different TLRs depending on the tissue context can lead to either a decrease or an increase in barrier function." (PMID 37997696, 2023). "Infection of IRAK4–/– reporter cells with A. baumannii or bacteria-free culture filtrate treatment resulted in complete loss of NF-κB activation suggesting that IRAK signaling is required for the activation of NF-κB during A. baumannii infection and culture filtrate treatment." (PMID 35615509, 2022). "Consistent with our results, another study performed an analysis of phosphorylated sequences within host cells and predicted activation of IRAK4 within 15 min of infection of Vero cells with SARS-CoV-2, and also revealed that a different inhibitor of IRAK1/4 impaired SARS-CoV-2 infection." (PMID 34857794, 2021). "To confirm this phenotype in a controlled situation, we utilized IRAK4-deficient mice to quickly ascertain their ability to survive infection by a Gram negative bacterium in vivo." (PMID 20105294, 2010). "This unpredicted clinical phenotype was validated by demonstrating that IRAK4-deficient mice had a similar resistance to infection with Gram negative S. typhimurium as wildtype mice." (PMID 20105294, 2010). "Our data could suggest that neuroinflammation in IRAK-4 deficiency may not always be due to infection, but rather as an inherent autoinflammatory feature caused by perturbation of this important signaling pathway." (PMID 37744344, 2023). "Mutations in some of the genes involved in TLR signalling, such as IRAK4, are compatible with life in both human and mouse in the absence of infection; however, in individuals carrying the mutations the innate immune response is reduced and sometimes not effective." (PMID 37997696, 2023). "Altered splicing of inflammatory and immune genes (e.g., IRAK4, MAP3K7, and CASP8) due to spliceosome mutations may contribute to MDS pathogenesis by leading to inflammation, changes in immune cell function, and increased risk of infection." (PMID 34196950, 2022). "The expression of Myd88, IRAK4, and TRAF6 mRNA in both WT and WUCI significantly increased and reached their peak when they were infected with A. hydrophila on day 1 post-infection." (PMID 40298788, 2025). "The expression of C6, C7, IRAK4, LBP, and RIPK2 was significantly upregulated after infection with A. hydrophila, while the expression of SIPA1L2 and NFATC1 was significantly downregulated after infection." (PMID 36910190, 2023).
infection (continued). "Significantly, our results showed that the expression of six major adaptor molecules (Myd88, IRAK2, IRAK4, TRAF3, TBK-1 and IRF7) downstream of RNA sensors were dramatically decreased in the PAMs with a PRRSV-ADE infection." (PMID 36680075, 2022). "For this purpose we evaluated the expression of TLR-2, MyD88, IRAK4, TRAF6, and TIRAP in macrophages at 48 hr after infection with H37Rv, BCG, H37RvΔRD-1 or H37RvΔESAT-6." (PMID 24475192, 2014). "Overall, impairment of the TLR7/MyD88/IRAK-4 pathway prevents pDCs from producing sufficient type I IFN in response to SARS-CoV-2 in the respiratory tract, accounting for the patients’ vulnerability to infections with this virus." (PMID 36880831, 2023). "To assess whether IRAK4 and TRAF6 are functional targets for Mtb to the induction of IL-8 production, we incubated the macrophages with an IRAK1/4 inhibitor prior to the infection." (PMID 31871425, 2019). "Similar to IRAK4, the notable changes in TRAF6 were observed 24 hours after infection." (PMID 31871425, 2019). "Therefore, during a short infection time, the IRAK4 and TRAF6 mRNA levels can be unaffected, then upregulated (24 hours), and finally downregulated after a prolonged infection time (48 hours)." (PMID 31871425, 2019). "As a negative regulator involved in innate immunity, along with induction of kinase activity of IRAK1/4 during infection, IRAK-M interacts with IRAK4 to induce transcription of downstream inhibitors such as A20, IĸBα, SOCS-1 and SHIP, to prevent radical immune pathology of the host." (PMID 28835201, 2017). "In addition, the activation of FcεRI-dependent mast cell via TLR4 recognition plays an important role in the E. granulosus infection at 4-hour post infection, as indicated by the hyperexpressed molecules, such as FcεRI, MCP1, MCP3, and IRAK-4." (PMID 26252489, 2015). "Indeed, the presence of severe neuroinflammation in our cases in the absence of infection implies that fully functional IRAK-4 likely plays an important role in the regulation of the inflammatory milieu within the CNS." (PMID 37744344, 2023). "In contrast, the older sibling with IRAK-4 deficiency demonstrated raised levels of CRP (192 mg/l; normal < 5 mg/l) and IL-6 (1983 pg/ml; normal < 7 pg/ml), potentially indicating a prolonged infection, a disease course which has also been reported in other IRAK-4-deficient patients with severe IPD." (PMID 24625087, 2014). "However, upon infection with SE, we found 11 of the TLR reference genes that were significantly up-regulated in heterophils from line A when compared to line B (MD-2, TIRAP, IRAK4, TRAF3, TAK1, IKKε, IKKα, NF-κB2, PI-3K, p38, and IRF7)." (PMID 22783275, 2012). "The presence of TLRs on the epithelial surface, in the absence of any infection, appeared to be able to trigger activation of the downstream pathway, as we could detect phosphorylated IRAK4 (p-IRAK4) in these cells, and p-IRAK4 levels increased with the cells reaching confluence and differentiating." (PMID 37997696, 2023). "In the current study, we reported that wild-type Mtb, but not the ∆choD strain, decreased the cytosolic IRAK4 and TRAF6 levels after prolonged (24 hours) infection." (PMID 31871425, 2019).